PPIAL4E (peptidylprolyl isomerase A like 4E)
Description:
PPIases accelerate the folding of proteins. It catalyzes the cis-trans isomerization of proline imidic peptide bonds in oligopeptides (By similarity).
Synonyms: COAS2
Gene: Protein-coding gene on chromosome 1 (144,372,875 to 144,373,634, reverse strand). Ensembl gene ENSG00000271567.
Subcellular location: Cytoplasm
Gene Ontology:
Molecular function: cyclosporin A binding; peptidyl-prolyl cis-trans isomerase activity
Biological process: protein folding
Cellular component: cytoplasm
Homologues: Orthologues: zebrafish ppifa (68% identical), zebrafish ppiab (68% identical), Caenorhabditis elegans cyn-3 (65% identical), Caenorhabditis elegans cyn-7 (65% identical), zebrafish ppiaa (64% identical), Caenorhabditis elegans cyn-2 (63% identical), Caenorhabditis elegans cyn-1 (60% identical), Caenorhabditis elegans cyn-9 (49% identical), Drosophila melanogaster Cyp40 (49% identical), Drosophila melanogaster Moca-cyp (46% identical). Paralogues in human: PPIAL4F (100% identical), PPIAL4D (99% identical), PPIAL4C (98% identical), PPIAL4A (98% identical), PPIAL4G (96% identical), PPIAL4H (96% identical), PPIA (85% identical), PPIF (66% identical), PPIE (61% identical), PPID (60% identical), PPIB (56% identical), PPIC (53% identical), and 10 more.